PIK3CA (phosphatidylinositol-4,5-bisphosphate 3-kinase catalytic subunit alpha)
Diseases named in the same sentence as PIK3CA in open-access papers (continued):
Sharing a sentence is not in itself a finding about the gene and the disease.
tumor (continued). "The pretherapeutic diagnostic evaluation of relapsed metastatic breast cancer includes the revision of the HER2 protein positivity (tumor genetic instability) by a biopsy of metastatic lesions and the identification of PIK3CA genetic mutations as well as the PD-L1 immune receptor." (PMID 39202767, 2024). "Even though the study sample is limited, the results suggest that 54% of the PIK3CA mutations were retained between the patients primary and relapse tumor, possibly indicating that a test could be beneficial already at the primary setting." (PMID 38822093, 2024). "Research has shown that PIK3CA mutations can modulate the anti-tumor immune microenvironment." (PMID 39329702, 2024). "Additionally, mutations in BRAF and PIK3CA are observed in some cases, indicating a shift toward a more aggressive tumor profile." (PMID 39768914, 2024). "Of the 25 patients identified with a PIK3CA mutation (including the one with a PIK3CA variant of unknown significance), 20 patients had tumor tissue DNA available, and 5 patients were tested with baseline cfcDNA." (PMID 38413796, 2024). "Interestingly, we previously presented compelling evidence for clinical response to the PI3K inhibitor, gedatolisib, in a metastatic BC patient with a HER2 + tumor harboring PIK3CA mutations, providing a proof-of-concept case." (PMID 39334392, 2024). "The mutations were more frequent in the relapse tumor setting during ongoing treatment, further supporting that testing of PIK3CA mutation status for PI3K inhibitor treatment should be carried out on the advanced tumor specimen for treatment in the advanced setting." (PMID 38822093, 2024). "Furthermore, mutations in the PIK3CA gene were associated with a decreased risk of tumour recurrence (Hazard Ratio: 0.26; 95% CI: 0.11–0.62; p = 0.018)." (PMID 39768623, 2024). "PIK3CA somatic mutations also show differences by ancestry in different tumor types." (PMID 38836758, 2024). "Furthermore, PIK3CA can serve as a marker of tumor differentiation and morphology, with increased PIK3CA expression being associated with low grade tumor histology and intestinal-type GCs." (PMID 38596668, 2024). "Secondly, PIK3CA gene mutation may affect the types and quantities of other tumor-associated antigens expressed by tumor cells, thereby affecting the efficacy of vaccines or cell therapy." (PMID 39555098, 2024). "This may be because the PIK3CA H1047R mutation is a stronger driver of tumor development than other types of PIK3CA mutations." (PMID 38344201, 2024). "In this study, it was observed that there is an increase in PD-1 receptor expression when there is PIK3CA mutation present, which could be accompanied by changes in tumor immunogenic properties." (PMID 38392199, 2024). "Furthermore, we aim to evaluate the association between the presence of the PIK3CA (H1047R) mutations and various clinical parameters, such as tumor grade and histological subtype." (PMID 39462049, 2024). "Consequently, investigations of PI3Ka inhibitors in early stage clinical trials across various tumor types harboring multi‐PIK3CA mutations have gained momentum." (PMID 39054873, 2024). "Very few molecular studies have assessed the mutational status of PIK3CA in feline tumours." (PMID 38787171, 2024). "For patients #8, #162, #200, #229, and #260, a phosphatidylInositol‐4,5‐bisphosphate 3‐kinase catalytic subunit alpha (PIK3CA) mutation was also found at relatively comparable concentrations, suggesting the presence of a tumor clone expressing both types of mutation." (PMID 38287892, 2024).
tumor (continued). "Notably, in TNBC, the mutation H1047R of PIK3CA has been linked to reduced complete tumor regression (pCR) rates when treated with anthracycline and taxane neoadjuvant chemotherapy." (PMID 38337803, 2024). "PIK3CA mutations were found in 5 patients’ (4, 5, 8, 10, and 11) tumor tissue." (PMID 38103030, 2024). "Future studies could aim to validate AutoEpiCollect’s vaccine design in murine models affected by PIK3CA-mutated or other mutated tumor cells located in various tissue types." (PMID 38671743, 2024). "Finally, the hazard of disease progression for patients with PTEN and/or PIK3CA mutated tumor biopsies was 2.02 (95% CI: 0.89–4.56; p = 0.092) times the hazard for participants with neither molecular event." (PMID 37210417, 2023). "Through activating mutations, gene amplifications, or rearrangements in PIK3CA and receptor tyrosine kinases or inactivating mutations in tumor suppressor genes, the PI3K/AKT/mTOR pathway, which regulates cell metabolism, proliferation, apoptosis, and autophagy, is altered in several malignancies." (PMID 36982568, 2023). "It is not a coincidence that the guideline update for biomarkers suggested that testing for PIK3CA mutations should use samples from tumor tissue or ctDNA in plasma to determine eligibility for treatment with alpelisib plus fulvestrant, a selective estrogen receptor degrader." (PMID 37760445, 2023). "Indeed, the combined presence of PTEN and PIK3CA or PIK3R1 mutations are frequently observed suggesting that both loss of tumor suppressor and activation of oncogenes is required during tumor progression." (PMID 37591832, 2023). "PIK3CA activating tumor mutations may occur in several domains of the p110α catalytic subunit, but mostly (≈80%) arise in four hotspots of the helical and kinase domains: E542K, E545K, H1047R, and H1047L." (PMID 36825198, 2023). "Somatic activating GOF PIK3CA point mutation is a tumor driver." (PMID 37109059, 2023). "Of the models sensitive to DIACC3010 (Group A), two had tumor growth inhibition that could be described as stasis, one of which harbored a PIK3CA mutation (GAX272)." (PMID 37749105, 2023). "PIK3CA amplification or mutations promote tumour infiltration and activate the PI3K/AKT/mTOR pathway, which suggests that PI3K/AKT/mTOR pathway activation might be related to resistance to 3rd-generation EGFR-TKIs." (PMID 37897649, 2023). "In addition, we found that the patients with tumours with mutations in PIK3CA, BRAF, CDH1, and NRAS exhibit better survival outcomes than those without mutations in these genes." (PMID 37550388, 2023). "They hypothesized that agents targeting PIK3CA mutations and other molecules downstream of the pathway might enhance chemotherapeutic sensitivity and accelerate tumor cell apoptosis." (PMID 36979714, 2023). "Therefore, LSD1 was up regulated upon PIK3CA mutation that resulted in tumor invasion and EMT features." (PMID 37580737, 2023). "The detection of tumor‐related mutations of PIK3CA exon could be achieved by the sequence‐specific recognition between the dCas9‐sgRNA‐modified biosensor and the target analyte and the assistance of EIS analysis." (PMID 39188296, 2023). "Notably, a promising tumor response was observed in the 6 mg QD group, particularly among patients with PIK3CA mutated tumors." (PMID 38037839, 2023). "A total of 17/45 tumor samples (37.8%) were found to carry a mutation in PIK3CA gene." (PMID 37821962, 2023). "PIK3CA mutations drive multiple signaling networks involving mTORC2-PKCζ-mediated activation of cPLA2, and cPLA2 inhibition and dietary fat restriction restore tumor immune cell infiltration and inhibit breast tumor growth." (PMID 36778122, 2023).
tumor (continued). "Two patients (9%) had tumours harbouring co-occurring PIK3CA mutations (one oncogenic E545K alteration and an E81K variant of unknown significance)." (PMID 36746967, 2023). "Only the combination treatment was efficient in inhibiting the tumor growth, suggesting that, whereas responses in patients with a PIK3CA preexisting mutation are possible, the PIK3CA E545K mutation contributes to the oncogenic signaling and its targeting seems relevant to maximize tumor response." (PMID 37377403, 2023). "Cancer is a frequent occurrence in PROS, and it is plausible that tumor cells with activating mutations in PIK3CA or MAP3K3 may infiltrate tissues and blood vessels in metastatic forms, leading to the formation of microvascular lesions such as CCMs." (PMID 37109059, 2023). "Here, we investigated a new treatment approach for CMT thusly: First, we confirmed the incidence of PIK3CA mutations in CMT cases, and the anticancer effect of a PIK3CA inhibitor was investigated by establishing novel canine cell lines from tumor tissues based on the presence of the mutation." (PMID 38033642, 2023). "Meanwhile, a series other assays used for adjuvant therapy were sprang up, such as Guardant 360 CDx assay (Guardant Health) based on simultaneous mutation detection of 55 tumor genes for pan‐cancer, and therascreen PIK3CA RGQ PCR Kit (QIAGEN Manchester) based on PIK3CA mutations for BC." (PMID 37492785, 2023). "Here, we showed that even lower alpelisib concentrations (10 ng/ml and 100 ng/ml) combined with low-dose metronomic VRL led to a significant reduction of cell viability of PIK3CA-mutated cells, and the anti-tumor activity was comparable with the effects at 1000 ng/ml alpelisib." (PMID 36998707, 2023). "This patient had a PIK3CA mutation conserved between the primary tumor and the metastasis." (PMID 36943861, 2023). "Another genetic hypothesis suggested that ECs of DVAs with GOF mutations in the PIK3CA gene have high somatic mutation potential as the known tumor driver mutation." (PMID 37109059, 2023). "EBV-positive tumours have a distinct molecular profile with high PD-L1 and PD-L2 expression, marked intra- or peritumoural immune cell infiltration, extreme DNA hypermethylation and recurrent PIK3CA mutations." (PMID 37370858, 2023). "If tumors are less ‘addicted’58 to mutations that occur late in tumor development, therapies targeted against PIK3CA mutations might be of limited effectiveness." (PMID 37081260, 2023). "An extensive NGS analysis of tumor tissue showed PIK3CA and HER2 mutations." (PMID 37893593, 2023). "Additionally, we found that PIK3CA mutations were present in about one-third of MKShi/ERSlo tumours, indicating a potential therapeutic option with PI3Kα-specific inhibitors such as alpelisib in this subgroup." (PMID 37935787, 2023). "In addition to AR overexpression and HRAS and PIK3CA-alterations, PD-L1 expression and Tumor Mutational Burden > 10 Mutations per Megabase were identified as additional potentially targetable alterations." (PMID 37427101, 2023). "PIK3CA mutations lead to the attenuation of tumor apoptosis and improvement of tumor invasion." (PMID 36238278, 2022).
tumor (continued). "However, the molecular mechanisms we uncovered here apply to other types of tumor types with a PIK3CA helical domain mutation as well." (PMID 35418124, 2022). "Furthermore, loss of PTEN, a PI3K‐regulator and tumor suppressor, is more frequent in the ultralow risk tumors, and PIK3CA‐mutations, which have been associated with more favorable outcome in ER‐positive breast cancer, are more common." (PMID 35179782, 2022). "PIK3CA mutations were detected in the metastatic and primary tumor." (PMID 36128324, 2022). "Therefore, it is imperative to delineate the comprehensive landscape of PIK3CA mutations across different tumor types and ethnicities." (PMID 35778737, 2022). "However, supporting the involvement of somatic cis-regulatory variants instead, we found smaller fold changes and less samples with imbalances measured at common PIK3CA variants in normal-matched tissue data than those measured at mutations in tumor tissue." (PMID 35676284, 2022). "In urothelial tumours somatic mutations in PIK3CA gene may be of use for early detection of primary and recurrent tumours in urine-based assays, not only for prognosis prediction, but also as molecular biomarkers for targeted therapies." (PMID 35317488, 2022). "Increasing evidence indicates that PIK3CA mutations can affect tumor progression." (PMID 35277182, 2022). "All of them were found to be PIK3CA mutated at the time of progression; each patient’s specific mutations were followed in the different circulating biomarkers in comparison with the corresponding tumor tissue." (PMID 35682999, 2022). "Moreover, 14% (7/50) of CRC patients whose tumours possess PIK3CA variants were predicted to respond to the PI3K pathway inhibitor." (PMID 36866106, 2022). "The prognostic effect of PIK3CA mutations was controversial in previous reports, and our results of the tumor stage-related prognostic effect might be a possible reason for the discrepant reports." (PMID 36071046, 2022). "PIK3CA mutations induce dedifferentiation of progenitor tumour breast cells into tumour stem cells." (PMID 35563449, 2022). "Interestingly, PIK3CA mutation in circulating tumor DNA (ctDNA) was detected in all patients, including those who tested negative for the mutation in the tissue (50%)." (PMID 36579519, 2022).
tumor (continued). "The mutational status of PIK3CA related to worse prognosis in the early stage but with better prognosis in the late-stage, although there was no significant varied frequency or distributions of mutational sites between tumor stages." (PMID 36071046, 2022). "Only 11.7% of TNBC tumours harboured a PIK3CA-mutation (15 of 128)." (PMID 36279023, 2022). "This pilot study investigates PIK3CA mutations in circulating tumor DNA (ctDNA), tumor cells (CTCs), and extracellular vesicles (EVs) with the aim of determining which information on molecular targetable profiling could be recollected in each of them." (PMID 35682999, 2022). "Mutation of PIK3CA can promote tumor cell invasion and increase the activity of downstream PI3Ks." (PMID 35840984, 2022). "As PIK3CA mutations are found to be more frequent in TNBC-expressing androgen receptors (40% of AR+ tumours vs. 4% in AR- TNBC), different trials have also evaluated the safety and efficacy of enzalutamide in association with the PI3K inhibitors alpelisib or taselisib." (PMID 35954393, 2022). "Additionally, the PIK3CA mutational analysis included both tumor biopsy samples and circulating tumor DNA (ctDNA), further complicating matters." (PMID 36046843, 2022). "We next analyzed concomitant genomic alterations in all tumor samples carrying PIK3CA mutations." (PMID 35778737, 2022). "Patients with PIK3CA-mutated tumours (n = 20) had lower pCR rates than wildtype tumours." (PMID 36279023, 2022). "Concomitant KRAS and PIK3CA mutations among the tumor, plasma, and peritoneal fluid in EC have been reported using targeted sequencing of gDNA derived from tissues and quantitative polymerase chain reaction (PCR) assay for ctDNA derived from the plasma and peritoneal fluid." (PMID 35626111, 2022). "More patients in this group died if their tumours were PIK3CA-mutated (11.4% and 8.5%, resp.)." (PMID 36279023, 2022). "In the tumor tissue, the mutational analysis revealed a p.(Hys1047Leu) PIK3CA mutation at 36.9% frequency, and the ctDNA NGS analysis validated the tissue mutation but also identified a second mutation in the ESR1 gene (p.(Asp538Gly), 0.39%), usually associated with endocrine resistance." (PMID 35682999, 2022). "In this trial, 112 patients with centrally confirmed PIK3CA mutations in tumor tissue were enrolled based on their previous treatment (CDKi + AI, CDKi + fulvestrant, or systemic chemotherapy or endocrine therapy): enrollment was completed in prior CDKi + AI and CDKi + fulvestrant SOC cohorts." (PMID 35565291, 2022). "Moreover, the drug combination inhibited tumor growth synergistically in CRCs with a PIK3CA helical domain mutation, but had only an additive effect on CRCs with either WT PIK3CA or a PIK3CA H1047R mutation." (PMID 35418124, 2022). "Some PIK3CA composite mutations have already been proved to increase cell proliferation, tumor growth but also PI3K inhibitor sensitivity in human breast epithelial cell lines, but to the best of our knowledge, it has not been linked to being the product of AID activity." (PMID 36456685, 2022). "As this tumor sample displayed a PIK3CA mutation, this might explain the overall only moderate response to ceritinib, despite being the only sensitivity detected in the zPDX model." (PMID 35159116, 2022). "PIK3CA mutations were mainly observed in early stages and high-grade tumours." (PMID 35317488, 2022). "In these tumor samples, the top 10 mutated genes included PIK3CA, MUC4, and TTN." (PMID 35528180, 2022). "Furthermore, our study provides evidence of the anti-tumor activity of PI3Kα inhibitors in a range of solid tumors, and especially in cancers harboring PIK3CA-specific mutations." (PMID 36385120, 2022).